KRAS (KRas proto-oncogene, GTPase)
Diseases named in the same sentence as KRAS in open-access papers (continued):
Sharing a sentence is not in itself a finding about the gene and the disease.
tumor (continued). "Due to recent findings that oncogenic KRAS can promote a metabolic reprogramming of tumor cells, several attempts to target KRAS-regulated metabolic process have also been developed." (PMID 35883626, 2022). "Next, to further clarify the biological implications of the KRAS mutation subtype, we performed ssGSEA/post-transcriptional modification (PTM) and Metascape analyses in the KM1 and KM2 tumor subsets at the RNA, protein, and phosphoprotein levels." (PMID 35836817, 2022). "HRAS and JAK1 mutations are less frequent in tumours with high NCS and KRAS mutations are under-represented in samples with high SCS." (PMID 35326573, 2022). "Another study indicated that 8-hydroxyguanine (8-OHG) released from ferroptotic cells recruits and activates tumor-associated macrophages (TAMs) to secrete IL-6 and nitric oxide synthase 2 (NOS2), promoting tumorigenesis of KRAS-driven PDAC." (PMID 35664778, 2022). "In agreement with our cell line findings, GSEA results show a positive enrichment of KRAS-mediated gene sets in the transcriptomes of METΔex14-mutant tumours compared to those with high-grade wildtype MET amplification." (PMID 35326531, 2022). "KRAS mutations lead to induced PD-L1 expression and increased CD8+ tumor-infiltrating lymphocytes, reducing tumor-specific T cell functions, which are correlated with an inflammatory TME." (PMID 36430176, 2022). "Although elevated macropinocytosis of KRAS mt tumor cells has been repeatedly verified by different laboratories, the levels are largely variable, and there is currently no conclusive answer to the exact extent of macropinocytosis enhancement by mutant KRAS." (PMID 35154489, 2022). "Our model was related to tumor TNM staging, pathological staging, and KRAS/BRAF mutational status and played an auxiliary role in the diagnosis and prognosis of CRC." (PMID 35619906, 2022). "Treatment of the non-small cell lung cancer (NSCLC) Calu-6 KRAS mutant xenograft model with AZD0364 at 50 mg/kg once daily (QD) for 21 days resulted in tumour regressions." (PMID 35617197, 2022). "So far, WT1 has been incriminated as a necessary contributor to KRAS-driven oncogenesis, demonstrating decisive regulatory roles regarding tumor cell responses (i.e., proliferation versus senescence) downstream of KRAS oncogenic signaling." (PMID 35453662, 2022). "De novo KRAS mutations reduce the sensitivity of colorectal cells to EGFR‐targeted therapy and CRC tumours also develop resistance to anti‐EGFR therapy by acquiring mutations in RAS." (PMID 34856074, 2022). "Based on the 33 tumor expression datasets, we conducted GSEA (genome set enrichment analysis) to show the KRAS and other co-expressed genes associated with cancers." (PMID 36330448, 2022). "The changes include the upregulation of ECM components such as matrix metalloproteinases (MMPs) and collagens, suggesting that KRAS is a driver of tumor desmoplasia." (PMID 36230914, 2022). "Pioneering work by Downward and colleagues has also shown tumor regression upon inhibition of the interaction between KRAS oncoproteins and the p110α subunit of PI3K." (PMID 34951114, 2022). "In Ephrin receptors, EFNA4 was conserved in EGFR-mut and KRAS-mut tumor while EFNA3 was conserved in EGFR-mut and NEK tumors." (PMID 36612014, 2022). "RMC-9805 reacts covalently with Asp12, thereby attenuating KRAS G12D downstream signaling specifically over KRAS WT and other KRAS mutants, and it restricts tumor growth in xenograft PDAC and CRC mouse models." (PMID 36531078, 2022). "Next, we quantified KRAS MAFs in tumour tissues from patients who underwent UFS, and found, as expected a high average value of 23 ± 20.5%." (PMID 35194118, 2022).
tumor (continued). "In KRAS-driven NSCLC, inactivation of tumor-suppressor gene STK11/LKB1 was associated with downregulation of PD-L1 and suppressed effector T-cells." (PMID 35884355, 2022). "Some factors in the univariable analysis were associated with longer DFS: age, Stages II or III, synchronous CRLM tumours, TBS, tumour number, KRAS status, R1 margin and preoperative chemotherapy." (PMID 35326950, 2022). "Tumor testing revealed clinically relevant molecular alterations, including the known germline pathogenic variant STK11, a KRAS somatic pathogenic variant, and FGFR3 gene amplification." (PMID 35543335, 2022). "In vivo, administration of RM-018 in H358 KRAS G12C-NSCLC xenograft models resulted in dose-dependent tumor regression and was well tolerated." (PMID 35251972, 2022). "We analyzed the prognostic value of each tumor sample according to the KRAS expression levels with different tumors." (PMID 36330448, 2022). "Targeting both wild-type and mutant KRAS in cancer has been notably unsuccessful; in particular, several high-throughput screens of KRAS-mutant cancer cell lines identified compounds which subsequently only partially reduced tumor volumes in xenograft models." (PMID 36513728, 2022). "Given the important role of the TME derived signals to drive tumor malignant features, these results indicate that KRAS targeted inhibition can partially abrogate the pro-tumorigenic stimuli derived from the TME." (PMID 35805073, 2022). "The KRAS-mutant tumor xenograft study in mice showed a clear distinction in the tumor eradicating potency between the VC and D-VC enantiomers." (PMID 36359850, 2022). "Using paired normal and tumor DNA from the same patients, we identified and validated a few novel recurrent somatic mutations in LGSOC, in addition to KRAS, BRAF, USP9X, and EIF1AX mutations that have been identified in previous studies." (PMID 36528667, 2022). "Pancreatic cells surviving KRAS oncogene ablation show features of dormant cells, are responsible for tumor relapse, and mostly rely on oxidative phosphorylation (OXPHOS) for survival." (PMID 35158815, 2022). "In this model, most mutations, including APC and KRAS, occur less often than in sporadic CRC and at later stages of tumor evolution, where they promote cytokine secretion, tumor growth, and angiogenesis via the NF-κB, IL-6/STAT3, or IL-23/Th17 pathways." (PMID 35884974, 2022). "KRAS and BRAF, the most widely studied oncogene mutations for CRC, should be an indispensable part of tumour analysis." (PMID 35326950, 2022). "Our study suggested that the interaction with coagulation system, KRAS signaling, and tumor neutrophil infiltration were the potential mechanisms of Sema3D serving as a tumor suppressor in ccRCC." (PMID 35813868, 2022). "In a recent report, a patient with metastatic G12D-mutated PDAC received adoptive cell transfer therapy using engineered autologous T cells that target KRAS G12D mutant protein in the tumor, resulting in regression of metastases in the patient." (PMID 36531078, 2022). "Anti-KRAS therapy also synergized with anti-PD-1 treatment and produced durable anti-tumor responses." (PMID 36531078, 2022). "Collectively, these results supported that, similar to drug-based KRAS inhibition, genetic Kras modulation selectively impacts tumor growth in vivo." (PMID 35327394, 2022). "In this carcinoma, DDX3X facilitates tumor metastasis enhancing the expression of the oncogene KRAS by promoting SP1 transcription factor binding to the KRAS promoter." (PMID 35954483, 2022). "According to our results, it can be reported that high grade of tumor budding is generally associated with poor prognostic factors (vascular and perineural invasion, distant metastases, MSS status, and KRAS mutations)." (PMID 35096426, 2022).
tumor (continued). "U1 overexpression lengthens the 3ʹUTR of KRAS to include a miRNA let-7 binding site with tumor-suppressive activity." (PMID 34489556, 2022). "For example, genetic tumor profiling revealed that people with KRAS who have a SNP in the 3’ UTR are more likely to develop NSCLC." (PMID 35885514, 2022). "The KRAS oncogene plays a crucial role in tumor initiation and maintenance, and its signaling network represents a significant target for therapeutic intervention." (PMID 36105100, 2022). "The KRAS expression was positively correlated with the histological grade, tumor extent, nodal status, and the pathological stage (r=0.712, 0.649, 0.646, and 0.865, respectively)." (PMID 36532636, 2022). "The mechanism of adoptive cell therapy is the targeting of human leukocyte antigen-matched mutant KRAS tumor cells instead of normal cells." (PMID 35517800, 2022). "Given the essential roles of KRAS in diverse cancers, we further systematically analyzed the correlation between KRAS and tumor immunity." (PMID 35563733, 2022). "Statins activate endoplasmic reticulum stress via inhibition of RAS prenylation, leading to enhanced immune responses against KRAS-mutant cancer cell lines and against KRAS-mutant tumours in the lung and liver of genetically engineered mouse models." (PMID 36111627, 2022). "Each patient’s sex, age, genetic mutation status (BRAF, NRAS, KRAS), and MSI status based on tumor genetic profiling; location of the primary tumor; site of metastasis; and time from diagnosis to death were collected from the hospital information system." (PMID 36136880, 2022). "We further analyzed the tumor biological signatures 39 to explore the representative immune and cancer-related processes within the KRAS-Mut subsets." (PMID 35836817, 2022). "Tumor organoids were generated from intestinal tumor tissues isolated from APC/KRAS compound mutant mice and cultured in 3D Matrigel with modifications." (PMID 35541903, 2022). "In the A549 xenografted mice, the treatment with αEGFR-mAB-P/KRAS-siRNA/P nanostructures led to significantly reduced tumour growth compared to control-siRNA loaded αEGFR-mAB-P/P nanostructures." (PMID 35220407, 2022). "A combination of anti-PD-1 immunotherapy with both sotorasib and adagrasib showed complete tumor regression in mice with KRAS G12C tumors." (PMID 36230484, 2022). "The association between KRAS and PD-L1 is important to discuss in regard to NSCLC, as these mutations often coexist and can affect tumor characteristics and therapeutic responses." (PMID 36136862, 2022). "Currently, Food and Drug Administration (FDA) has approved an allele-specific covalent inhibitor of KRAS (G12C), AMG510 (sotorasib) having marked clinical responses across multiple tumor types." (PMID 35922812, 2022). "KRAS signaling downregulation was part of a tumor inhibition pathway, and anticancer inhibitors targeting the KRAS signaling pathway have been developed." (PMID 36170029, 2022). "In low-WM score group, the top genes with the highest mutation frequency were KRAS (26%), TTN (26%), and MUC16 (24%), showing that the high-WM score group had more tumor mutation burden than the low-WM score group." (PMID 35154267, 2022). "KRAS is a well-validated anti-cancer therapeutic target, whose transcriptional downregulation has been demonstrated to be lethal to tumor cells with aberrant KRAS signaling." (PMID 36011352, 2022). "Together, our findings reveal numerous mechanisms of resistance to current KRAS G12C inhibitors through enrichment of clonal populations, KRAS-independent downstream signaling, and diverse remodeling of the tumor microenvironment." (PMID 34990404, 2022). "This study has shown that KRAS were significantly different in 12 tumor tissues compared to normal tissues." (PMID 36330448, 2022).
tumor (continued). "Along with high KRAS mutation rates and RAS84 expression, RAG-1 was characterised by STK11/LKB1 mutations (KL tumours) and RAG-4 by CDKN2A mutations (KC tumours)." (PMID 36163168, 2022). "Recent studies showed that besides its function in cancer cells, KRAS oncogenic signaling can orchestrate the immune status of the tumor microenvironment." (PMID 35075146, 2022). "Previous studies have demonstrated that KRAS knockdown results in apoptotic cell death in several KRAS-mutant tumor-derived cell lines, showing that some cancer cells require KRAS to maintain viability." (PMID 35883626, 2022). "Focusing on a set of driver mutations that interact with KRAS to initiate aggressive, sarcomatoid-type ICC revealed that tumor growth relies on Wnt and PI3K signaling." (PMID 35074757, 2022). "The improved version of this drug, ARS-1620, demonstrated the tumor growth control in a KRAS G12C xenograft model by its additional H-bond interaction with H95 in the switch pocket and a more favorable alignment of the warhead toward C12." (PMID 36359850, 2022). "The mean diameter of lung metastases in our study were 8.1 mm, which according recent studies, is below the 10 mm threshold needed for lung metastases to shed sufficient tumor DNA fragments to allow detection by KRAS ddPCR or targeted deep sequencing." (PMID 34994972, 2022). "Certain tumour molecular characteristics, such as CpG island methylator phenotype (CIMP), microsatellite instability (MSI) and somatic mutations in BRAF and KRAS, have been widely investigated with regard to the heterogeneity of diet and CRC association." (PMID 35998061, 2022). "Here, we review convergent and diverse metabolic networks related to oncogenic KRAS mutations between PDAC initiation and progression, emphasizing the interplay among oncogenic mutations, glucose metabolic reprogramming, and the tumor microenvironment." (PMID 36151074, 2022). "Preclinical studies have demonstrated that limiting the availability of copper dependence is an effective strategy for blocking KRAS-driven and autophagy-dependent tumor growth and survival in copper dysregulated diseases." (PMID 36209249, 2022). "This suggests that senescence is triggered in response to oncogenic activation of KRAS and acts to constrain PanIN progression and tumour development." (PMID 35418690, 2022). "The SK-LU1 tumour growth was significantly inhibited when mice were treated with αEGFR-mAB-P/KRAS-siRNA/P nanostructures compared to PBS control group and to αEGFR-mAB-P/control-siRNA/P nanostructures." (PMID 35220407, 2022). "Tumor mutational burden (TMB) was also evaluated considering different cut-offs, and we found a significant association between TMB and STK11 and KRAS mutations." (PMID 35625958, 2022). "Particularly, the pro-tumor signals including KRAS, TGF-β, and hypoxia pathways showed significant positive relationship with GC progression." (PMID 36561311, 2022). "Overwhelming evidence supports the cooperation of mutant KRAS and Myc in metabolic reprogramming and therapeutic resistance through the tumor microenvironment." (PMID 35307764, 2022). "In vitro and in vivo experiments have verified that the tumor suppressor role of miR-96 depends on its inhibitory effects on KRAS." (PMID 35139853, 2022). "iRGD exosomes were also employed to precisely transport KRAS siRNA to v3-containing A549 tumors in vivo, resulting in specific KRAS gene knockdown and tumor growth reduction." (PMID 39698444, 2022).
tumor (continued). "MUC5AC was found to be a significant determinant of a poor prognosis, especially in KRAS-mutant tumours." (PMID 36059804, 2022). "The results showed that ATO/D-VC is capable of inhibiting tumour growth of the KRAS G12D mutant PDAC cancers." (PMID 36619305, 2022). "In additional five tumor cases, KRAS VAFs ranged from 0.8% to 18.5% in bulk samples, 0.3% to 20.3% in cored samples, and 6.0% to 26.7% in LMD tumor samples were observed." (PMID 36266629, 2022). "It was shown that spectral CT has the potential to predict KRAS and EGFR mutations as well as ALK reordering in solid lung adenocarcinoma, thus accurately reflecting molecular features of this tumour." (PMID 35406429, 2022). "The combination of SHP2 and KRAS G12C inhibition induced favorable but tumor site-specific changes in the immune microenvironment, increasing CD8 + T cells, decreasing myeloid suppressor cells, and sensitizing tumors to PD-1 blockade." (PMID 36508072, 2022). "A significant difference between two genotypes occur at stage 1, in which KRAS+ tumor cells displayed more normal nucleocytoplasmic ratios, perhaps due to slightly larger cell size and smaller nuclei compared to EGFR+ cells." (PMID 36201559, 2022). "KRAS selectivity and the therapeutic effects of dextran-conjugated TP were investigated via both in vitro cellular studies and in vivo tumor model assessment." (PMID 35154474, 2022). "In the genomic analysis, effective enrichment of neoplastic cellularity revealed by high KRAS VAF scores was found in LMD as well as cored tumor tissues obtained from certain bulk tumor tissues containing different amount of cellularity." (PMID 36266629, 2022). "On the other side, DRP1 knockdown has been shown to inhibit fragmented mitochondria phenotype and tumor cell growth in vitro, in mouse xenograft, and in a genetically engineered mouse model of KRAS-driven pancreatic cancer." (PMID 35565283, 2022). "To do so, we characterized cell and organelle volumes and shapes of epithelial cells in situ within EGFR+ and KRAS+ types across three stages of tumor progression, and compare them to normal AT2 cells." (PMID 36201559, 2022). "The main applications that are under investigation concern the reduction of drug resistance, the utilization of exosomes as drug-carries, the therapeutic modification of the immune tumor microenvironment, and the targeting of KRAS." (PMID 35408980, 2022). "This treatment method yielded significant tumor regression and clinical improvement in patients with KRAS G12D metastatic CRC and metastatic melanoma." (PMID 35014625, 2022). "CMS4 demonstrated upregulated KRAS signaling, supporting a tumor cell autonomous mechanism of cetuximab resistance in the absence of KRAS gain of function mutations." (PMID 35538548, 2022). "This pattern was similar but more pronounced than seen in KRAS mutant/wild-type colorectal cancer, another immune-cold tumor." (PMID 36290818, 2022). "Subpopulations of tumor cells exhibited signatures of proliferation, KRAS signaling, cell stress and epithelial-to-mesenchymal transition." (PMID 35995947, 2022). "Although PDAC cells generally exhibit abnormally fragmented mitochondria due in part to the expression of the oncogene KRAS the role of mitochondrial fusion in this tumor remains controversial." (PMID 35565283, 2022). "Here, we utilized a bioinformatics analysis and identified overexpression of KRAS/MMP7/CD44 oncogenic signatures in CRC tumor tissues compared to normal tissues." (PMID 35203586, 2022).